AR (androgen receptor)
Diseases named in the same sentence as AR in open-access papers (continued):
Sharing a sentence is not in itself a finding about the gene and the disease.
neuroblastoma (19 papers, 2011 to 2025). Neuroblastoma (NB) is the most common solid, extracranial childhood tumor. "As to LINC00622, it is tightly associated with transcriptional factor androgen receptor and essential neuroblastoma progression." (PMID 38240708, 2024). "Therefore, we tested the effects of overexpressing Mid1 on the level of pathogenic AR protein in the mouse Neuroblastoma-Spinal Cord hybrid (NSC) 34 cell line." (PMID 35821212, 2022). "ZMIZ1 is a coactivator of the androgen receptor (AR), which has been shown to regulate transcriptional activity of the μ-opioid receptor in both rats and human neuroblastoma cell lines." (PMID 40937335, 2025). "The human neuroblastoma cell line SH-SY5Y with low expression of AR protein was stably transfected with AR-overexpression plasmid or control plasmid and then treated with BPA or vehicle control." (PMID 36803626, 2023). "Knockdown of LINC00622 in EVs reduced tumor growth in nude mice injected with neuroblastoma cells possibly by regulating the expression of gamma-aminobutyric acid type A receptor subunit rho1 (GABRR1) via the androgen receptor (AR)." (PMID 35202087, 2022). "Targeting AR-SCAP-SREBPs-HMGCR/CYP17A1 axis will provide a novel strategy for neuroblastoma treatment." (PMID 34041015, 2021). "Such AR-independent actions of androgens have been described in several cell types, including macrophages, T cells and neuroblastoma cells." (PMID 33478524, 2021). "Our previous study reported that the androgen receptor (AR) promotes the growth of neuroblastoma in vitro and in vivo." (PMID 34041015, 2021). "Clinical samples and Oncomine database analysis proved the activation of AR–SCAP–SREBPs-CYP17/HMGCR axis in neuroblastoma." (PMID 34041015, 2021). "In humans, oxytocin/AR co-labeled neurons are also found in the PVN and T treatment of a human neuroblastoma cell line reduces oxytocin mRNA through an AR-mediated mechanism." (PMID 32727567, 2020). "Although it has been illustrated that androgen receptor (AR) was expressed in neuroblastoma cells in some former reports, the biological role of androgen receptor in the development of neuroblastoma is not fully understood." (PMID 28326012, 2017). "These showed R1881 promote the migratory ability of both neuroblastoma cell lines while AR knockdown, ARN509 and MDV3100 suppress the migratory ability." (PMID 28326012, 2017). "The neuroblastoma cells were treated with R1881 (10 nM), a synthetic agonist of AR, or the antagonists of AR, ARN509 (10 μm), and MDV3100 (10 μm) for 72 h." (PMID 28326012, 2017). "Intriguingly, with vehicle treatment, AR expressed in both the cytoplasm and nucleus suggesting the constitutive AR activity in neuroblastoma cells." (PMID 28326012, 2017). "More important, our result indicates the anti-tumor role of MDV3100 and ARN509 on neuroblastoma cells by targeting AR as well as provides insight into the anti-androgen treatment of neuroblastoma." (PMID 28326012, 2017). "The present study indicated that AR agonist R1881 obviously promoted cell proliferation, migration, invasion and sphere formation of both neuroblastoma cell lines, SH-SY5Y and N2a, in vitro and the progression of N2a in vivo." (PMID 28326012, 2017). "The result supported our hypothesis that AR signaling promoted the progression of neuroblastoma specifically." (PMID 34041015, 2021). "It is still unknown that whether the expression of the six genes, AR, SCAP, SREBF1, SREBF2, HMGCR, and CYP17A1 are closely associated with neuroblastoma patient survival." (PMID 34041015, 2021). "However, the role of androgen receptor (AR) signaling pathway in molecular pathogenesis of neuroblastoma is rarely reported." (PMID 28326012, 2017). "Thus, we propose another mechanism that AR signaling increases MMPs expression and consequently promotes invasion of neuroblastoma cells." (PMID 28326012, 2017).
neuroblastoma (continued). "In spite of too limited ganglioneuroblastoma (GNB) specimens were acquired, the activation of this AR-SCAP-SREBPs-HMGCR/CYP17A1 axis was specific in NB distinct from other neuroendocrine or neuroblastic tumors." (PMID 34041015, 2021). "Moreover, the promoting and suppressing effects of AR agonist and antagonists, respectively, had been evidently attenuated by inhibition of endogenous AR expression, suggesting that AR signaling pathway may take part in the progression of neuroblastoma." (PMID 28326012, 2017). "Besides, it suggested neuroblastoma cells produce hormones to induce the growth of their own, which explained the nuclear expression of AR with vehicle treatment as well as administration of AR antagonists can achieve better growth inhibition compared with the vehicle." (PMID 28326012, 2017). "Thus, we can reasonably infer activated AR signaling may induce tubulin expression leading to neuroblastoma growth." (PMID 28326012, 2017). "Neuroblastoma cells, treated with 1 nM DHT or 1 nM estradiol, were employed for the ChIP assays using anti-AR or anti-ERα antibody, respectively." (PMID 21359227, 2011). "Vehicle (DMSO)-treated cells grew well, but slow, that suggests AR activity is important but not the unique factor to neuroblastoma cells' growth." (PMID 28326012, 2017). "Neuroblastoma cell lines exhibited high level of AR expression while no AR expression was detected in HeLa or Raw264.7 cells." (PMID 28326012, 2017). "Several studies have shown that GRP/GRP-R targeted therapy inhibits neuroblastoma tumor growth and both AR positive and negative PC tumors." (PMID 27542219, 2016). "Therefore, we speculate that activation of AR signaling induces VEGF production so as to promote proliferation and migration of the neuroblastoma cells." (PMID 28326012, 2017). "In NEPC with the absence of the AR, KDM4B could interact with N-Myc instead, where it has been shown to regulate and epigenetically activate this oncogene in neuroblastoma." (PMID 29757368, 2018).
alopecia (18 papers, 2009 to 2025). Hair loss usually from the scalp. "There have been reports of pharmacological activities, including anti-alopecia via the inhibition of an androgen receptor, a hepatoprotector, by activating the NRF2/ARE signaling pathway." (PMID 37630348, 2023). "Group FEA-3 was identified by LC-MS/MS-QTOF, followed by molecular docking to the androgen receptor (PDB: 4K7A), causing alopecia." (PMID 36559008, 2022). "Predicated on an in silico test, the compounds that acted as an anti-alopecia using androgen receptor (PDB: 4K7A) were Compounds 2, 3, and 4 supported by ADME-Tox properties with good results." (PMID 36559008, 2022). "This research successfully identified potential compounds from the subfraction of Sansevieria trifasciata Prain leaves as anti-alopecia treatment in inhibiting androgen receptor activity based on LC-MS/MS analysis and computational studies." (PMID 35889232, 2022). "Increasing evidence on the pathogenesis of alopecia has demonstrated that 5α-dihydrotestosterone (5α-DHT) binds to the androgen receptor on DP cells resulting in progressive follicular miniaturization, shortening of the anagen phase, and hair loss." (PMID 34099599, 2021). "Extensive studies have supported the intricate relationship between FPHL, local androgen concentrations, and androgen receptor sensitivity, revealing higher rates of local testosterone and DHT production by the 5αRD isoenzyme type II in alopecia-prone areas of susceptible individuals." (PMID 39594244, 2024). "Moreover, DHT was revealed to cause alopecia via suppression of the Wnt/β-catenin signaling pathway by activating GSK-3β, and PTGDS is induced by the androgen receptor (AR)." (PMID 36831222, 2023). "Excessive production of DHT by SRD5A2, which is a representative cause of male pattern hair loss, induces the expression of DKK1, an inhibitor of the Wnt signaling pathway, via AR stimulation, which ultimately leads to the blockade of the Wnt signaling pathway." (PMID 35784391, 2022). "We also investigated AR inhibition based on molecular docking and dynamics simulations to ascertain the potency of the bioactive compounds from Sansevieria trifasciata Prain as an alopecia drug candidate." (PMID 35889232, 2022). "Our findings suggest that PF4 inhibits human hair follicle growth probably by promoting androgen receptor signaling and downregulating hair growth-promoting genes, providing thoughtful insights into the application and optimization of PRP in hair loss treatment." (PMID 32953277, 2020). "Therefore, bufotalinin, a steroid compound, is a potential androgen receptor antagonist and could be useful in the treatment of alopecia." (PMID 35978863, 2022). "Therefore, differences in thyroid antibody titers between men with and without alopecia are probably associated with a direct action of testosterone on the androgen receptor and do not seem to be mediated by aromatization to estradiol." (PMID 34106452, 2021). "Moreover, the AR-DHT complex promotes the transcription of TGF-β1/-β2, and DKK-1, resulting in hair follicle miniaturization, shortened anagen phase, and eventual follicle regression leading to alopecia." (PMID 39000592, 2024).
motor neuron disease (18 papers, 2008 to 2024). "Spinal bulbar muscular atrophy (SBMA) is an adult-onset, slowly progressive motor neuron disease caused by abnormal CAG repeat expansion in the androgen receptor (AR) gene." (PMID 32070397, 2020). "Dynactin-1 mRNA is also reduced in the affected neurons of a mouse model of spinal and bulbar muscular atrophy, a motor neuron disease caused by triplet CAG repeat expansion in the gene encoding the androgen receptor." (PMID 22312314, 2012). "SBMA is an inherited motor neuron disease caused by the expansion of a polyglutamine tract within the androgen receptor (AR)." (PMID 20525284, 2010). "In spinal and bulbar muscular atrophy (SBMA), an inherited motor neuron disease caused by the expansion of a polyglutamine tract within the androgen receptor (AR), the mutant AR is an Hsp90 client protein that forms a molecular complex with the chaperone." (PMID 20938400, 2010). "Spinal and bulbar muscular atrophy (SBMA) is an inherited motor neuron disease caused by the expansion of a polyglutamine tract within the androgen receptor (AR)." (PMID 19090995, 2008). "Repeat expansions in different loci can also yield similar phenotypic features, making them difficult to distinguish clinically: repeat expansions in at least ten spinocerebellar ataxia genes frequently present as adult-onset ataxia, and those in C9orf72 and AR can both cause motor neuron disease." (PMID 35182509, 2022). "To elucidate the role of FUS/TLS in polyQ diseases, we crossed FUS/TLS heterozygous mice with transgenic (TG) model mice of both HD and spinal and bulbar muscular atrophy (SBMA), a motor neuron disease caused by a CAG/polyQ expansion of the androgen receptor (AR)." (PMID 27739513, 2016). "Spinal and bulbar muscular atrophy (SBMA) is an X-linked and adult-onset inherited motor neuron disease caused by abnormal cytosine-adenine-guanine (CAG) repeat expansions, which encode polyglutamine (polyQ) tracts in the androgen receptor (AR) gene." (PMID 35052449, 2022). "For example, in seven patients with amyotrophic lateral sclerosis or other motor neuron disease, expansions were identified in AR (n=4) and C9orf72 (n=3)." (PMID 35182509, 2022). "Here we focus on chromosome 9 open reading frame 72 (C9ORF72) and androgen receptor (AR) genes which are similarly affected by repeat expansions, leading to two different kinds of motor neuron disorders, namely ALS and SBMA, respectively." (PMID 32512809, 2020). "We further exploited another motor neuron disease model, spinal and bulbar muscular atrophy (SBMA), which is a currently untreatable motor neuron disease caused by the expansion of a polyglutamine (polyQ) repeat in the androgen receptor (AR)." (PMID 32527063, 2020). "Abnormalities in the nuclear pore complex have recently been described in ALS, and these defects may contribute to the abnormal subcellular localization of specific proteins linked to motor neuron diseases, such as fused in sarcoma (FUS), TAR DNA-binding protein 43 (TDP-43) and AR." (PMID 28087734, 2017). "Lastly, diminished AR expression in spinal motor neurons, which links to another motor neuron disorder, spinal bulbar muscular atrophy (SBMA), may contribute to ALS pathogenesis and suggests a common disease pathway in ALS and SBMA mediated by disruption of AR signalling in motor neurons." (PMID 25889790, 2015).
salivary gland carcinoma (18 papers, 2015 to 2025). A carcinoma that arises from the major or minor salivary glands. "One‐third of SDCs are positive for human epidermal growth factor receptor 2 (HER2), and almost all SDCs are positive for androgen receptor (AR), both of which are rarely found in other types of salivary gland cancer." (PMID 38477487, 2024). "Remarkably, 17 AR-positive salivary gland cancer patients who received ADT showed a 64.7% overall response rate, of which three showed a complete remission." (PMID 35517428, 2022). "A number of patients with AR-positive salivary gland carcinoma have been treated with anti-androgen therapy." (PMID 30382367, 2019). "To date, there have been a handful of case reports/series documenting favorable outcomes in patients with salivary gland cancers treated with AR-directed therapies." (PMID 28085048, 2017). "A single arm Phase II study testing enzalutamide in AR-positive salivary gland cancers is ongoing [clinicaltrials.gov: NCT02749903]." (PMID 28085048, 2017). "In this review, we describe the prevalence, biology, and therapeutic implications of androgen receptor signaling in salivary gland cancer." (PMID 28208703, 2017). "In our case, complete anti-androgen blockade with bicalutamide plus LHRH was chosen as the optimal therapy at the time, based on AR expression of the tumor and reported literature on salivary gland carcinomas." (PMID 25699235, 2015). "Abiraterone is active as a second line ADT in AR+ salivary gland cancer and might represent an additional treatment strategy for the here reported subgroup." (PMID 37427101, 2023). "Moreover, the uniform expression of AR in malignant salivary gland carcinoma has been demonstrated 62-66." (PMID 35517428, 2022). "However, we could find some studies stating that anti-HER2 and anti-AR therapies were effective in salivary gland carcinoma in small-scale studies." (PMID 29564569, 2018). "Accumulating evidence in malignancies suggests the aberrant expressions of the estrogen receptor (ER) and the androgen receptor (AR) in HNC, such as in laryngeal cancer and cancer of the salivary gland." (PMID 35517428, 2022).
type 2 diabetes (18 papers, 2005 to 2025). "In addition, by regulating lipid biosynthesis and energy homeostasis, the androgen receptor is involved in pathophysiological processes with dysregulated lipogenesis, such as obesity and type 2 diabetes." (PMID 31925559, 2020). "Importantly, as Amlexanox has already been administered to humans in a clinical trial for Type 2 diabetes, repurposing this drug in PC patients who are resistant to AR targeting therapies could be tested quickly." (PMID 32324216, 2020). "Furthermore, the increased androgen receptor expression may enhance binding to androgenic hormones, testosterone, and DHT in the skeletal muscle in type 2 diabetes." (PMID 27832095, 2016).
ovarian tumors (17 papers, 2006 to 2025). "The expression of MMP-2 and MMP-9 showed a significant association with the presence of androgen receptor in the epithelium of the total ovarian tumors." (PMID 32718331, 2020). "Shorter repeats of the CAG segment have been associated with an increased expression of the AR gene in ovarian tissue and another study presented a Western Blot analysis of tissue cultures as evidence that increased expression of AR gene is associated with ovarian tumor formation." (PMID 22151998, 2011). "Further studies involving these cases are therefore required to determine the status of AR expression in various subtypes of ovarian tumors and its prognostic impact in both low and high grade/stage tumors." (PMID 30791431, 2019). "In surgical specimens, earlier studies using ligand binding assays indicated AR positivity in 85 (90.4%) of 94 and 75 (91.5%) of 82 ovarian tumors." (PMID 30791431, 2019). "We determined that the AR and Nanog expression levels in ovarian tumors were higher than those in the ovaries." (PMID 29716628, 2018). "One study demonstrated dissimilar AR reactivity within a single ovarian neoplasm, attesting to tumor heterogeneity [S105]." (PMID 25595907, 2015). "Network analysis of the human signalling pathways suggests the importance of the AR gene, which is down-regulated in ovarian tumor samples, leading to cancer." (PMID 23383610, 2013). "AR expression in primary ovarian tumors and metastases was quite similar, suggesting that downregulation of AR occurs early in ovarian carcinogenesis." (PMID 20565760, 2010). "Although it has been hypothesized that AR-positive ovarian tumors may also preferentially respond to treatment with AR antagonists, it remains to be determined whether AR status could serve as a reliable prognostic biomarker in this disease model." (PMID 40392873, 2025). "AR immunoreactivity was also detected in 40% of benign epithelial neoplasms and 61% of adenocarcinomas, as well as in 64% of ovarian neoplasms (8 serous carcinomas, 3 endometrioid carcinomas, 2 mucinous carcinomas, 1 granulosa tumor), obtained from women undergoing oophorectomy." (PMID 30791431, 2019). "Moreover, using Pearson’s correlation analysis, we found that the correlation coefficient (R) between AR and Nanog was 0.61, indicating that AR and Nanog expression was correlated in ovarian tumor tissues." (PMID 29716628, 2018). "AR was expressed strongly in the cytoplasm and nucleus of ovarian tumor cells." (PMID 29716628, 2018). "Both AR and Nanog expression were obviously high in ovarian tumors." (PMID 29716628, 2018). "We hypothesize that the protein network including PCBP1 contributes to the malignant properties of ovarian tumors, possibly through regulation of the androgen receptor." (PMID 25265318, 2014). "Nine out of the ten ovarian tumors displayed variable cytoplasmic immunoreactivity with AR." (PMID 17020615, 2006). "However, only AR expression correlates with the clinical parameter of histopathological grade that represents the degree of differentiation in cancer cells, where AR is detected more frequently in the low grade 1 and 2 tumors than in the high grade 3 ovarian tumors." (PMID 34502188, 2021). "Although further information will be required in order to explain the relationship between AR and MMP-2 in ovarian tumors." (PMID 32718331, 2020). "Using survival analysis, we also report that the set of three genes, CHEK1, AR, and LYN, can be used in the prognosis of ovarian tumors." (PMID 23383610, 2013). "The role of testosterone treatment in tumour progression is uncertain as a putative role for androgens and the AR in the development or proliferation of ovarian tumours has not been established." (PMID 33106582, 2021).
ovarian tumors (continued). "The analysis of this cohort provides evidence of the presence of MMP-2 and MMP-9 in the epithelium and stroma of ovarian tumors, showing variations in the presence of MMPs when stratified by histological subtypes, FIGO stages and expression of AR, ERα, and PR in the ovarian tumor as well." (PMID 32718331, 2020). "Compared with the negative signals in the normal ovarian tissues, AR was strongly expressed in the cytoplasm and nucleus of ovarian tumor cells." (PMID 29716628, 2018).